ZNF77 (zinc finger protein 77)
Description:
May be involved in transcriptional regulation.
Synonyms: pT1
Tractability: PROTAC: ubiquitination databases record sites on it.
Gene: Protein-coding gene on chromosome 19 (2,933,218 to 2,944,971, reverse strand). Ensembl gene ENSG00000175691.
Subcellular location: Nucleus
Subcellular location (Human Protein Atlas): Nucleoli; Nucleoplasm
Pathways (Reactome):
Gene expression (Transcription): Generic Transcription Pathway
Gene Ontology:
Molecular function: protein binding; DNA-binding transcription factor activity, RNA polymerase II-specific; RNA polymerase II transcription regulatory region sequence-specific DNA binding
Biological process: regulation of transcription by RNA polymerase II; regulation of DNA-templated transcription
Cellular component: nucleus
Genetic constraint (gnomAD): Loss-of-function variants: 15 observed, 13.86 expected, observed/expected ratio (o/e) 1.08, 90% interval 0.72 to 1.65. The upper end of that interval is the gene's LOEUF score, 1.65, which puts it in group 6 of 6, group 1 being the genes least tolerant of losing a copy. Missense variants: 717 observed, 702.96 expected, observed/expected ratio (o/e) 1.02, 90% interval 0.96 to 1.09. Synonymous variants: 282 observed, 255.52 expected, observed/expected ratio (o/e) 1.1, 90% interval 1 to 1.22.
Homologues: Orthologues: chimpanzee ZNF77 (98% identical), macaque ZNF77 (94% identical), Drosophila melanogaster CG3281 (23% identical), Drosophila melanogaster CG2712 (22% identical), Drosophila melanogaster Phs (21% identical), mouse BC025920 (9% identical). Paralogues in human: ZNF555 (50% identical), ZNF69 (40% identical), ZNF440 (40% identical), ZNF778 (39% identical), ZNF266 (39% identical), ZNF439 (39% identical), ZFP37 (38% identical), ZNF599 (38% identical), ZFP90 (38% identical), ZNF404 (37% identical), ZNF805 (37% identical), ZNF20 (37% identical), and 50 more.
Diseases named in the same sentence as ZNF77 in open-access papers:
ZNF77 is named in the same sentence as 53 diseases in open-access papers, as found by Europe PMC text mining. Sharing a sentence is not in itself a finding about the gene and the disease. The quoted sentences say what the papers report.
asthma (2 papers, 2020 to 2025). "Overall, these changes made cells carrying the ZNF77 variant more receptive to A. fumigatus infection, suggesting that ZNF77-genotyping of patients with asthma may be useful as a risk-marker for ABPA." (PMID 32482729, 2020).
Obesity (1 paper, 2015). Accumulation of substantial excess body fat. "Thereby we identified a premature stop codon in MYO1A associated with higher hs-GH and lower measures of obesity as well as higher levels of HDL-C and one premature stop codon of ZNF77 associated with higher hs-GH and height." (PMID 26086970, 2015).
osteosarcoma (1 paper, 2022). A usually aggressive malignant bone-forming mesenchymal neoplasm, predominantly affecting adolescents and young adults. "In order to determine which lncRNA was involved in osteosarcoma, lncRNAs including lnc-SELPLG-2:1, lnc-DDX47–3:1, lnc-ZNF77–165:3, lnc-SRSF2–9:2, lnc-SAMD11–1:1, and lnc-PPP1R9B-4:2 were detected by RT-qPCR to determine if their sequences were consistent with sequencing results." (PMID 36199080, 2022).
ZNF77 also shares sentences with these, for which no sentence is quoted: tumor (20 papers); infection (9); cancer (7); ovarian carcinoma (3); prostate carcinoma (3); Diabetes (2); Hypertension (2); myopathy (2); viral infection (2); AIDS (1); Atrophy (1); Autoimmunity (1); bacterial infections (1); bone metastasis (1); breast carcinoma (1); cardiomyopathy (1); cardiovascular disease (1); Cognitive impairment (1); colon cancer (1); combined immunodeficiency (1); complement deficiency (1); developmental delay (1); head and neck cancer (1); hyper-IgM syndrome (1); hypertrophic cardiomyopathy (1); Intellectual disability (1); Krabbe disease (1); leukemia (1); Leukoencephalopathy (1); liver cancer (1).
A further 20 diseases each share a sentence with ZNF77 in 1 paper.